STAG2 (STAG2 cohesin complex component)
Diseases named in the same sentence as STAG2 in open-access papers (continued):
Sharing a sentence is not in itself a finding about the gene and the disease.
Ewing sarcoma (continued). "STAG2-mutant glioblastoma cells have been previously shown to be sensitive to PARP inhibition in vitro, and cohesin mutations may be potential biomarkers of PARP sensitivity in bladder cancer and Ewing sarcoma, where these mutations are common." (PMID 33351783, 2021). "While STAG2 mutational activation is known to be frequent in glioblastoma, Ewing sarcoma, and urothelial carcinoma, the effect of STAG2 status on the response to cytotoxic chemotherapy agents routinely used in the treatment of these cancer types is largely unknown." (PMID 30975996, 2019). "We observed that STAG2-mutant cells were strongly dependent on STAG1, as has been recently reported in the context of bladder cancer and Ewing sarcoma cell lines." (PMID 33351783, 2021). "We show that the synthetic lethal interaction between STAG1 and STAG2 is observed in isogenic HCT 116 and KBM-7 cells as well as in bladder cancer and Ewing sarcoma cell lines." (PMID 28691904, 2017). "Together, these findings reveal that STAG2 loss reprograms, rather than globally attenuates, EWS-FLI1 function, amplifying a high-risk oncogenic transcriptional state in Ewing sarcoma." (PMID 41950086, 2026). "Altered EWS::FLI1 dependent transcription is unlikely to explain all the changes that are important in promoting the more aggressive phenotype of Ewing sarcoma in patients lacking STAG2." (PMID 39487368, 2024). "In our study, we show that pediatric cancer tumor types other than Ewing’s sarcoma also demonstrate sensitivity to PARP inhibition, independent of STAG2 mutation or EWS-FLI1 fusion." (PMID 37020198, 2023). "Gain of RAD21 copy number due to trisomy 8 was found to reduce replicative stress and support the growth of Ewing sarcoma cells harboring EWSR1-FLI1, and this effect was independent of STAG2 mutation status." (PMID 34202641, 2021). "A previous study reported absence of STAG2 protein expression in cell lines derived from a range of cancers (glioblastoma, Ewing's sarcoma, melanoma, haematologic, cervical and renal) and identified mutations or homozygous deletion in several of these." (PMID 24270882, 2014). "We next obtained gene expression data for several clones of the Ewing sarcoma cell line A673, with and without STAG2, generated by CRISPR editing and verified by sequencing and by immunoblotting with antibodies directed against the amino and carboxi-terminal regions of the protein (Fig. EV1A,B)." (PMID 39487368, 2024). "In Ewing sarcoma A673 cells, non-CTCF cohesin sites were detected with an antibody against SMC1, but they showed little enrichment for RAD21, STAG1 or STAG2." (PMID 36424654, 2022).
bladder cancer (35 papers, 2014 to 2025). "The pro-tumorigenic contributions of STAG2 in bladder cancer underlie the importance of identifying therapeutic vulnerabilities of STAG2 expressing cells to develop novel precision therapies for bladder cancer patients." (PMID 40025053, 2025). "We successfully validated the interaction of NIDP2 and STAG2, a cohesion complex member and well-established cancer gene associated with various malignancies, including acute myeloid leukemia and bladder cancer." (PMID 38747635, 2024). "For example, low STAG2 expression in muscle-invasive bladder cancer patients had been demonstrated to be associated with less progression compared to high STAG2 expression." (PMID 35371307, 2022). "Stromal antigen 2 (STAG2) is one of 12 genes significantly mutated in four or more cancer types, and is mutated in approximately 10% of bladder cancers." (PMID 36275363, 2022). "Early studies in bladder cancer cell lines indicated that STAG2 loss was associated with alterations in modal chromosome number." (PMID 36275363, 2022). "The analysis of a bladder cancer tissue microarray (n = 346) revealed that decreased STAG2 protein expression is associated with improved overall and progression-free survival for patients with MIBC." (PMID 36275363, 2022). "Here, using whole-exome and targeted sequencing (n = 119 bladder cancer clinical samples), we found several STAG2 mutations in MIBC that correlate with loss of protein expression." (PMID 36275363, 2022). "STAG2 is frequently mutated across several different cancer types, and here we show that it is frequently mutated in bladder cancer." (PMID 36275363, 2022). "One of the most commonly mutated genes in bladder cancer is STAG2, which encodes the cohesin subunit STAG2." (PMID 33923108, 2021). "STAG2, a component of the mitotically essential cohesin complex, is highly mutated in several different tumour types, including glioblastoma and bladder cancer." (PMID 34462321, 2021). "We transplanted STAG2 mutated (p.K983*) UM-UC-3 bladder cancer cells, which were transduced with in vitro validated shRNAs targeting STAG1, into immunocompromised mice to evaluate the effects of partial STAG1 suppression in vivo." (PMID 32467316, 2020). "STAG2 (stromal antigen 2), a subunit of cohesion, was significantly and commonly mutated or lost in bladder cancer, mainly in tumors of low stage or grade, and its loss was associated with improved outcome." (PMID 32842545, 2020). "Restoration of STAG2 expression in a mutated bladder cancer model alleviates the dependency on STAG1." (PMID 28691904, 2017). "Lentiviral transduction of a FLAG-STAG2 transgene into STAG2 mutated UM-UC-3 bladder cancer cells resulted in the restoration of STAG2 expression, nuclear localization of the transgenic protein and its incorporation into the cohesin complex." (PMID 28691904, 2017). "Our data indicate that loss of STAG2-cohesin function in mediating chromatid cohesion is unlikely to be the major effect of mutational inactivation in bladder cancer." (PMID 24270882, 2014). "A recent study reporting STAG2 mutations in bladder cancer included an immunohistochemistry screen across a broad panel of tumor types." (PMID 24484537, 2014). "We have identified a high frequency of inactivating mutation of STAG2 in bladder cancer, with a significant association with low tumour grade and stage." (PMID 24270882, 2014). "In bladder cancer, STAG2 mutations are most common in the earliest low-grade lesions, suggesting that mutational inactivation of STAG2 may be an initiating event." (PMID 41091719, 2025). "STAG2 mutations, other than nonsense and frameshift, may lead to loss of tumor suppressor properties and a gain of tumor-promoting functions in bladder cancer." (PMID 36275363, 2022). "In bladder cancer, STAG2 loss of expression is associated with recurrence and disease prognosis." (PMID 35371307, 2022). "The correlation between STAG2 mutations and aneuploidy in bladder cancer is also unclear." (PMID 34621263, 2021).
bladder cancer (continued). "Amongst solid tumors, STAG2 mutations show the highest prevalence in bladder cancer." (PMID 32467316, 2020). "Therefore, we have carried out a mutation analysis of the entire coding sequence of STAG2 and assessed STAG2 protein expression in a large panel of bladder cancers and cell lines." (PMID 24270882, 2014). "Notably, truncating mutations in STAG2 have been shown to be one of the most common genetic lesions in bladder carcinoma." (PMID 24484537, 2014). "STAG2, which is encoded on the X chromosome, represents the most frequently mutated cohesin subunit in human cancers with predominantly deleterious alterations detected in 15–20% of bladder cancer and Ewing sarcoma tumors and in ∼6% of acute myeloid leukemia and myelodysplastic syndrome cases." (PMID 32467316, 2020). "Thus, we hypothesize that the loss of STAG2 in the context of non-invasive bladder cancer has major impact on a cell-cycle and DNA repair-independent function." (PMID 24270882, 2014). "We find that inactivation of STAG2 in bladder cancer cells and in bladder epithelial precursor cells resulted in concomitant inactivation of the H3K27me3 Polycomb chromatin mark." (PMID 41091719, 2025). "Conversely, no studies have identified a specific targetable vulnerability in cases of high STAG2 expression, which is particularly urgent in bladder cancer where STAG2 acts in an oncogenic manner." (PMID 40025053, 2025). "This study provides new insights into the role of STAG2 in the pathogenesis of bladder cancer, demonstrating roles for STAG2 in the regulation of Polycomb-mediated epigenetic regulation and in the differentiation of bladder epithelial precursor cells." (PMID 41091719, 2025). "Following this, comparisons were made between groups to identify drugs that were significantly more effective in STAG2 high or STAG2 low expressing bladder cancer cell lines." (PMID 40025053, 2025). "After querying drug sensitivity data of over 4500 drugs in 24 bladder cancer cell lines from the DepMap database, we found that cells with less STAG2 mRNA expression are more sensitive to ATR and CHK inhibition." (PMID 40025053, 2025). "Cell lines were classified as STAG2 high or STAG2 low based on the median expression of the total collection of bladder cancer cell lines." (PMID 40025053, 2025). "Previous work from our group and others supports the notion that STAG2 acts in an oncogenic manner in bladder cancer." (PMID 40025053, 2025). "In the current study, we sought to uncover therapeutic vulnerabilities of muscle invasive bladder cancer cells based on the expression of STAG2." (PMID 40025053, 2025). "Next, we analyzed the effect of STAG2 modulation on tumor growth in vivo using bladder cancer cell line–derived xenografts." (PMID 36275363, 2022). "Therefore, we investigated whether STAG2 loss alters bladder cancer cell movement in vitro." (PMID 36275363, 2022). "have found that STAG2, ESPL1 and NIPBL genes with frequent mutations in bladder cancer are involved in the SCCS process." (PMID 34094968, 2021). "STAG2, ESPL1 and NIPBL genes with frequent mutations in bladder cancer are involved in the sister chromatid cohesion and segregation process." (PMID 34094968, 2021). "The STAG2 protein expression status in the panel of bladder cancer cell lines was confirmed using immunoblotting." (PMID 28691904, 2017). "siRNA experiments revealed that STAG2 status represented a predictive marker for the sensitivity to STAG1 depletion across the bladder cancer cell line panel." (PMID 28691904, 2017). "Similar results were also obtained in a bladder cancer cell line with shRNA-mediated depletion of STAG2." (PMID 26871722, 2016). "Gene editing was used to generate cultured human cancer cell lines that differ only in the presence or absence of bladder-cancer derived STAG2 mutations." (PMID 41091719, 2025).
bladder cancer (continued). "It is established that STAG2 acts in a pro-tumorigenic manner in bladder cancer, and therefore STAG2 may exert an oncogenic function through regulation of PI3K signaling in bladder cancer cells." (PMID 40025053, 2025). "Based on results of high throughput compound screening with a well annotated library of drugs, we characterize STAG2-dependent signaling pathways that confer sensitivity and may promote bladder cancer." (PMID 40025053, 2025). "Together, these data imply that STAG2 acts in an oncogenic manner in bladder cancer." (PMID 40025053, 2025). "Therefore, our overall objective for the current study was to identify therapeutic vulnerabilities based on STAG2 expression in bladder cancer cells." (PMID 40025053, 2025). "STAG2 is often mutated in bladder cancer, with a higher frequency of mutations in non-muscle invasive bladder cancer (NMIBC) than in muscle invasive bladder cancer (MIBC)." (PMID 40025053, 2025). "In mutant bladder cancer models, restoring STAG2 expression mitigated dependence on STAG1." (PMID 39390002, 2024). "Therefore, we sought to investigate the consequences of STAG2 alterations for patients with bladder cancer." (PMID 36275363, 2022). "Initially, we screened 18 different bladder cancer cell lines for STAG2 protein expression." (PMID 36275363, 2022). "In this study, we show that patients with MIBC whose tumors have low STAG2 protein expression have improved OS and PFS, suggesting that the level of STAG2 expression may influence bladder cancer initiation or progression." (PMID 36275363, 2022). "STAG2 expression is associated with decreased MIBC survival and may be a useful biomarker to guide bladder cancer treatment." (PMID 36275363, 2022). "STAG2 is frequently referred to as a tumor suppressor; however, our results and those of others indicate that STAG2 may drive oncogenic changes in bladder cancer." (PMID 36275363, 2022). "To determine whether the level of STAG2 protein expression impacts patient outcomes in bladder cancer, we utilized a TMA comprised of 346 muscle-invasive and non–muscle-invasive bladder tumors." (PMID 36275363, 2022). "In additional, C2 shows higher STAG2 mutant rates, which is reportedly correlated with poor prognosis in BLCA; STAG2 has also been shown to regulate the cell cycle progression of bladder cancer cells, suggesting that the C2 group may respond to chemotherapy." (PMID 36245985, 2022). "STAG1 depletion prevented colony formation and abolished sister chromatid cohesion selectively in STAG2 mutated UM-UC-3 (F983fs) but not in STAG2 wild-type UM-UC-5 bladder cancer cells." (PMID 28691904, 2017). "Furthermore, we and others have shown that stable depletion of STAG2 in bladder cancer cells leads to alterations in chromosome counts." (PMID 26871722, 2016). "The mechanism by which STAG2 acts in a pro-oncogenic manner in bladder cancer remains unknown." (PMID 40025053, 2025). "We utilized the well-established HB-CLS-1 cell line and a patient derived bladder cancer cell line, BO1, which both have endogenous expression of STAG2." (PMID 40025053, 2025). "This suggests that, compared with STAG2+ cells, STAG2− cells are more dependent on STAG1 on a large, context-independent scale, a finding consistent with previous knockdown of STAG1 in bladder cancer and Ewing’s cell line panels." (PMID 34462321, 2021). "Among the candidate molecules associated with urothelial differentiation are KRT20, a well established luminal marker, and FGFR3, STAG2, and PIK3CA—three major bladder cancer genes commonly altered in luminal tumors." (PMID 32635360, 2020). "In line with previous literature in bladder cancer, STAG2 KO did not significantly alter the degree of T24 cell proliferation." (PMID 40025053, 2025).
bladder cancer (continued). "We validated the STAG2 and CDKN1A changes detected by whole-genome sequencing using Sanger sequencing in the discovery set of tumours, and then undertook replication testing in a set of 35 additional bladder cancers." (PMID 24777035, 2014). "A growing body of literature suggests that STAG2 deletion or loss-of-function truncating mutations sensitize cancer cells to PARP inhibitors, including olaparib, rucaparib, and veliparib, although to date these studies have not been conducted in bladder cancer." (PMID 40025053, 2025). "However STAG2, but not STAG1, has been identified as a tumour suppressor in leukaemia, sarcoma, glioblastoma and bladder cancer." (PMID 28430577, 2017).
glioblastoma (30 papers, 2013 to 2026). The most malignant astrocytic tumor (WHO grade IV). "Here, we report the presence of STAG2 variants in patients with glioblastoma and medulloblastoma and determined the effects of loss of STAG2 in human cells and of the homolog SA1 in Drosophila tissues." (PMID 41502392, 2026). "Here we report the impact of stable correction of endogenous, naturally occurring STAG2 mutations on gene expression, 3D genome organization, chromatin loops, and Polycomb signaling in glioblastoma multiforme (GBM)." (PMID 38705393, 2024). "This concept has been confirmed in glioblastoma, in which cells containing STAG2 mutations show increased sensitivity to a combination of PARP inhibitors and DNA-damaging agents." (PMID 36275363, 2022). "In contrast, mutations of STAG2, encoding a subunit of the cohesin complex controlling sister chromatid separation during cell division, were scattered among almost all glioblastoma subgroups." (PMID 34572759, 2021). "Meanwhile, STAG2-mutated glioblastoma cells are more easily destroyed by PARP inhibitors when using temozolomide, a DNA-damaging drug." (PMID 33077733, 2020). "Initial studies in glioblastoma cell lines suggested a role for STAG2 mutations as a cause of chromosomal instability and aneuploidy during tumorigenesis." (PMID 30975996, 2019). "STAG2 or other mutations in the cohesion complex were observed also in other tumors, including glioblastoma, myeloid malignancies, colon cancer and bladder cancer." (PMID 26193259, 2015). "In the recent study of STAG2 in glioblastoma, a clear effect of STAG2 loss of function on the generation of aneuploidy was found." (PMID 24270882, 2014). "For example, STAG1-deficient mouse embryo fibroblasts show increased aneuploidy, and functional assays in glioblastoma cell lines have linked loss of STAG2 expression to chromatid cohesion defects and aneuploidy." (PMID 24270882, 2014). "Additionally, STAG2 is considered an important tumor suppressor gene, with its deletion being associated with various cancers such as glioblastoma multiforme (GBM), Ewing's sarcoma, and melanoma." (PMID 39510176, 2024). "However, in a recent study performed in glioblastoma cell lines, an opposing effect of STAG2 mutation was reported." (PMID 39594644, 2024). "In glioblastoma, the function of STAG2 has been related to maintenance of euploidy via its role in the cohesin complex." (PMID 24270882, 2014). "Additionally, upregulation of several growth factors and oncogenes was reported in STAG2 mutant glioblastoma cells, which were downregulated upon STAG2 correction." (PMID 39594644, 2024). "Correction of the mutant STAG2 allele in two aneuploid glioblastoma cell lines restored normal chromatid cohesion." (PMID 39594644, 2024). "STAG2 mutation has previously been reported in one Ewing sarcoma tumor and in multiple EFT cell lines and has additionally been reported as a recurrently mutated tumor suppressor gene in other tumor types including glioblastoma, urothelial carcinoma, and acute myeloid leukemia." (PMID 25010205, 2014). "Robust STAG2 expression has been shown in non-neoplastic tissues while significant fractions of glioblastomas had completely lost expression of STAG2, suggesting that miR-21 may have both oncogenic and tumor-suppressive effects." (PMID 23358700, 2013). "Our examination of two glioblastoma cell lines (U138MG and H4 cells) that naturally do not express STAG2 indicates that both are defective in the cGAS-STING pathway." (PMID 29662124, 2018). "In glioblastoma cells, a correlation between PARP1 sensitivity and the presence or absence of the cohesin complex gene STAG2 was demonstrated." (PMID 26193259, 2015).